MYLIP (myosin regulatory light chain interacting protein)
Diseases named in the same sentence as MYLIP in open-access papers (continued):
Sharing a sentence is not in itself a finding about the gene and the disease.
viral infection (1 paper, 2024). "Given the evolutionarily conserved activity of MYLIP between zebrafish and mammals, mammalian MYLIP may have similar function as zebrafish mylipb in response to viral infection." (PMID 38739631, 2024).
tumor (14 papers, 2017 to 2025). "MYLIP expression has already been identified in pericytes in other contexts, such as in transcriptomic data of tumours and single-cell profiling of lung tissue." (PMID 37047406, 2023). "Four genes (CENPH, MYLIP, PITX3, and TRAF3IP3) were eventually identified; these were associated with tumor-infiltrating immune cells, the proliferation of tumor cells, and cell adhesion." (PMID 34631307, 2021). "Our study indicated that MYLIP was a tumor suppressor during the progression of LUAD, and hypoxia promoted DNA methylation of MYLIP." (PMID 32031203, 2020). "Then we extracted the RNA from the tumor tissues and tested the relative expression levels of miR-19b and MYLIP in miR-19b agomir group and agomir control group respectively." (PMID 28969074, 2017). "By regulation of LncRNA SGMS1-AS1 and miR-106a-5p38, MYLIP, a potential tumor suppressor gene in LUAD, may prevent the proliferation, invasion, and migration of LUAD cells." (PMID 37427142, 2023). "In the next step, we conducted the immunohistochemical (IHC) staining for tumor samples to detect the expressions of MYLIP and cell adhesion molecules (E-Cadherin, ICAM-1 and Integrin β1) and let the pathologists to determine their relative IHC scores in miR-19b agomir and agomir control groups." (PMID 28969074, 2017). "In our study, the majority of neoepitopes that could activate TIL had not gained binding affinity to HLA-A2 compared to the corresponding wild-type peptide; only for the AGPS and MYLIP peptides from the KADA tumor was an increased binding observed, as confirmed by HLA-A2 stabilization assays." (PMID 31921104, 2019). "The results show that KRT8, PSMD2, TRIM28, and UBE2V2 are significantly overexpressed in tumor tissues, while the expression level of FBXO9, MYLIP, and RNF180 is significantly reduced in LUAD (p < 0.05)." (PMID 35711913, 2022).
cancer (6 papers, 2017 to 2022). A tumor composed of atypical neoplastic, often pleomorphic cells that invade other tissues. "MYLIP (myosin regulatory light chain interacting protein), an E3 ubiquitin ligase, which is associated with the regulation of cell motility and migration, has been found to play a critical role in malignant tumors." (PMID 35711913, 2022). "Also, the inhibition of MYLIP downregulation by TUSC8 resulted in suppressed metastasis showing the important role of MYLIP in cancer." (PMID 32899424, 2020). "Thus, apart from exploring the interactions between MYLIP and cell adhesion molecules contributing to cancer metastasis, the modulatory mechanisms of MYLIP in cancer metabolism are also worthwhile paying more attention in the cancer metastasis research field." (PMID 28969074, 2017). "Moreover, for the crucial role of MYLIP and its relationship with the cell adhesion molecules in cancer metastasis, it is a quite new research field and much things still need to be done to reveal the real mystery under them." (PMID 28969074, 2017). "Using the bioinformatics databases to predict the downstream targets of miR-19b, we noticed that a novel target gene, myosin regulatory light chain interacting protein (MYLIP), has the high score ranks and might participate in the processes of cancer metastasis." (PMID 28969074, 2017).
infection (2 papers, 2021 to 2023). The state of being infected such as from the introduction of a foreign agent such as serum, vaccine, antigenic substance or organism. "As previously demonstrated, infection causes significant recruitment of SIRT2 to the TSSs of MYLIP, ERRC5, LEF1, SYDE2 and EHHADH but not ARAP2." (PMID 34929015, 2021).
MYLIP also shares sentences with these, for which no sentence is quoted: atherosclerosis (10 papers); cardiovascular disease (3); diabetes (3); hyperlipidemia (3); lung adenocarcinoma (2); Alzheimer disease (1); amyloid (1); carotid atherosclerosis (1); cognitive deficits (1); glioblastoma (1); Hepatic steatosis (1); Hepatitis (1); lung diseases (1); neurodegenerative disease (1); pancreatitis (1); papillary thyroid carcinoma (1); peripheral vascular disease (1); spinal cord injury (1); systemic sclerosis (1); thyroid cancer (1).